IL2RG (interleukin 2 receptor subunit gamma)
Diseases named in the same sentence as IL2RG in open-access papers (continued):
Sharing a sentence is not in itself a finding about the gene and the disease.
Respiratory tract infection (1 paper, 2025). An infection of the upper or lower respiratory tract. "Six cases of IL2RG gene mutation combined with T. marneffei infection were identified in the literature, most showing fever, hepatosplenomegaly and respiratory tract infection." (PMID 41164818, 2025).
schizophrenia (1 paper, 2022). A major psychotic disorder characterized by abnormalities in the perception or expression of reality. "Another study explored the relationship between IL-2RG gene and schizophrenia." (PMID 36138890, 2022).
Sepsis (1 paper, 2024). Sepsis is defined as life-threatening organ dysfunction caused by a dysregulated host response to infection. "The results indicated that ITGAM, CD44, C3AR1, and IL2RG exhibited significantly higher expression in the sepsis group compared to the SIRS group." (PMID 38678059, 2024). "Furthermore, a meta-analysis identified four genes, namely ITGAM, CD44, C3AR1, and IL2RG, which were highly expressed in the sepsis group compared to the normal group (P < 0.05)." (PMID 38678059, 2024).
skin infection (1 paper, 2025). An inflammatory process affecting the skin, caused by bacteria, viruses, parasites, or fungi. "Previous studies have suggested that mutations in IL2RG gene may be associated with virus-derived skin infections." (PMID 40019657, 2025).
steatosis (1 paper, 2022). Increased lipid within the cytoplasm of cells. "A recent study has shown that Il2rg-/-/Rag2-/-/Fah-/- mice with a humanized liver fed a high fat diet (41% kcal fat) developed higher steatosis than mice fed a control diet." (PMID 35533183, 2022).
teratoma (1 paper, 2017). A non-seminomatous germ cell tumor characterized by the presence of various tissues which correspond to the different germinal layers (endoderm, mesoderm, and ectoderm). "These RAG2 SCID pigs successfully formed human iPS-derived teratoma whereas Rag2-/- mice or IL2RG-/Y mutated pigs failed to form teratoma." (PMID 29050212, 2017).
tuberculosis (1 paper, 2024). A chronic, recurrent infection caused by the bacterium Mycobacterium tuberculosis. "In our systemic review, we outline the efficacy of systemic anti-tuberculosis therapy, hematopoietic stem cell transplantation, and gene therapy in children with SCID and BCG diseases caused by IL2RG gene mutation." (PMID 39176082, 2024).
uterine fibroids (1 paper, 2022). "Another SNP on chromosome X (rs7052106), located between genes IL2RG and MED12, is associated with uterine fibroids and several other traits, including mean platelet volume, reticulocyte traits, and platelet distribution width, as well as total testosterone levels." (PMID 36579561, 2022).
uveal melanoma (1 paper, 2021). A melanoma derived from melanocytes of the uveal tract. "In human HGF knock-in NOD.Cg-Prkdc scid Il2rg tm1Wjl/SzJ mice, combination of CDK4/6 inhibitor and cMET inhibitor showed significant growth suppression in implanted metastatic uveal melanoma cells, compared to CDK4/6 inhibitor alone." (PMID 33806615, 2021).
wasting syndrome (1 paper, 2024). "The wasting syndrome and skeletal phenotype associated with SHIP1 deficiency were ameliorated in immunodeficient mice lacking RAG2 and IL2RG." (PMID 38388173, 2024).
WHIM syndrome (1 paper, 2022). "Innate immune cells (e.g., NK cells and neutrophils), which play a role in elimination of virus infection response, are affected in LAD1 deficiency, IL2RG/JAK3 deficiency, and WHIM syndrome." (PMID 35665206, 2022).
tumor (99 papers, 2009 to 2026). "Expression levels of CD40LG and IL2RG presented borderline significant association values with tumor size." (PMID 38831317, 2024). "Herein, through a comprehensive approach combining integrative bioinformatics analysis with rigorous experimental validation, we present a novel tumor immune-associated gene, defined as IL-2RG." (PMID 38720389, 2024). "PRKCSH deficiency augmented the antitumor effects of natural killer (NK) cells, representative TNFSF effector cells, in a tumor xenograft IL-2Rg-deficient NOD/SCID (NIG) mouse model." (PMID 38200153, 2024). "In the UPS TME, T cells expressed the ETS1 and IL2RG genes associated with resistance to gemcitabine and tumor metastasis, respectively." (PMID 39685635, 2024). "Future and on-going studies will utilize these data to refine and optimize orthotopic tumor engraftment with these cell lines in the RAG2/IL2RG deficient pigs." (PMID 34478363, 2022). "Next, we show results from a recently developed immunocompromised RAG2/IL2RG deficient pig tumor model that better mimics human anatomy and physiology compared to mouse models." (PMID 34478363, 2022). "Previous studies have shown that the development of immunodeficient mice with mutations targeted at IL2Rg chain gene allows engraftment of the primary human tumor types." (PMID 32817844, 2020). "As in Il2rg-/- mice that are genetically deficient for NK cell production, tumor cells engrafted more efficiently in Rag1-/- mice that had been depleted of NK cells with NK1.1 antibody compared to control antibody treated Rag-/- mice." (PMID 30936429, 2019). "Subcutaneous tumor growth has been demonstrated in a proof-of-principle study with implantation of human PC cells (Panc01) into the ears of immunodeficient transgenic pigs (RAG2/IL2RG deficient)." (PMID 36579622, 2023). "Following confirmation of the formation of a HN in the F344 Il2rg Rag2 double KO rat model, an orthotopic OS tumour was induced within the HN of the eight remaining rats." (PMID 41315643, 2025). "We examine the effects of ASNS deletion on tumor growth and the subsequent rewiring of metabolic pathways in male and female Rag2/IL2RG mice." (PMID 38886847, 2024). "Given IL-2RG’s pivotal role in regulating lymphocytes, our study set out to evaluate its significance within the context of tumor-infiltrating lymphocytes." (PMID 38720389, 2024). "This study delves into the role of Interleukin-2 receptor gamma (IL-2RG) within the tumor microenvironment and investigates potential microRNAs (miRNAs) that directly inhibit IL-2RG, aiming to discern their impact on CRC clinical outcomes." (PMID 38720389, 2024). "The result indicated that the IL-2RG was significantly correlated with the patient’s gender, location of the tumor, and pathological differentiation (all p-values < 0.05)." (PMID 38720389, 2024). "We identified IL2RG as a target enriched in classical tumor epithelium and has previously shown to attenuate PanIN growth through JAK3 suppression in orthogonally implanted pancreatic cancer." (PMID 37633924, 2023). "IHC staining showed stronger expression of CD3D, CD3E, CXCR3 and IL2RG in tumor tissue compared to normal tissue." (PMID 37509334, 2023). "LS174T tumor cells were orthotopically implanted into the cecum of NSG mice, which, due to IL2rg deficiency along with NOD and SCID mutations, lack T, B, and NK cells in addition to hyporesponsive innate immune cells." (PMID 37559947, 2023). "The fact that curcumin is a suppressor of miR-155 in tumor cells and a restorer of IL2RG in blood cells holds the potential to be an effective preventive therapy against cancer formation in BRCA1-metylation carriers." (PMID 37240365, 2023). "The decreased expression of IL2RG induces T cell apoptosis among T cells in the peripheral blood, resulting in lowered anti-tumor immunity." (PMID 37240365, 2023).
tumor (continued). "We examined the extent to which EBAG9 downregulation affected the anti-tumor response of BCMA CAR T cells in a NOD.Cg-Prkdcscid Il2rg tm1 Wji/Szj (NSG) mouse xenotransplantation model." (PMID 35821635, 2022). "IL-15 is a potent stimulator of CD8+ T cells and NK cells via the activation of IL-15Rα, IL-2Rβ (also named CD122), and IL-2Rγ (also named CD132), which share receptors with IL-2, IL-4, IL-7, IL-9, and IL-21, and thereby reduces tumor burden." (PMID 36439125, 2022). "The antitumor response of NMD inhibition was dependent on the immune system, as tumor kinetics of 4T1 SMG1KD was similar to the control when implanted in immunodeficient mice (Rag2/IL2rg-/-)." (PMID 36443756, 2022). "Initial studies have focused on refining the imaging and targeting healthy organs with histotripsy in preparation for planned tumor ablation studies in the RAG2/IL2RG knockout orthotopic pig model." (PMID 34478363, 2022). "MOLM-13 cells expressing either CSF2RB shRNA or control shRNA were injected subcutaneously into the flanks of Rag2/Il2rg-mutant mice and tumor growth was monitored by caliper measurements." (PMID 34750506, 2022). "Further genotyping of this animal revealed only a partial disruption of the RAG2 and IL2RG genes, resulting in an attenuated but still viable immune system that drove tumor rejection." (PMID 34478363, 2022). "Here, we summarize our recent studies in using the IL2RG KO hamsters as a host for human tumor tissue engraftment to produce patient-derived xenograft (PDX) models as laboratory avatars for oncology research." (PMID 35954238, 2022). "To functionally test this, we implanted E0771 cancer cells into the mammary gland of C57Bl/6 mice deficient in T, B and NK cells [Rag2−/−::Cd47−/−::Il2rg−/−; triple knockout (TKO)] and compared the tumor growth to tumors in WT C57Bl/6 mice." (PMID 33653826, 2021). "Most importantly, we found that IL2RG−/Y pigs supported the growth of human cancer cells and the formation of human tumours." (PMID 32871045, 2020). "Rag2/IL2rg-/- double knockout impelled SCID in mice; next, we attempted to transplant various human-tissue-derived primary and passage tumor cells into these mutated mice." (PMID 31134127, 2019). "Taken together, our findings suggest Rag2/IL2rg-/- double-knockout mice represent an ideal xenograft tumor model, as this mouse type showed compromised growth of various tissue-derived cancer cells and different inoculation methods." (PMID 31134127, 2019). "Similar to tumors receding in C57BL/6: Rag1-/- mice, tumor regression in C57BL/6: Rag1-/-; Il2rg-/- mice also was typified by a significant culling of GFP-positive tumor cells and a concomitant increase in fibrosis." (PMID 30936429, 2019). "Not only does IL-1B appear positively correlated with MAP17 in all tumors, other interleukins including IL-15, IL-18, IL-1A, IL-32 and IL-7 and interleukin receptors including IL-10RB, IL-17RC and IL-2RG appear in at least three of the tumor types." (PMID 29228712, 2017). "RMS tumors were generated from the different RMS cell lines by subcutaneous engraftment in NOD/Scid IL2rg-/- mice, and tumor growth was monitored." (PMID 27548722, 2016). "Here, we studied VGSC expression in tumours following orthotopic implantation of luciferase-expressing MDA-MB-231 cells into the mammary fat pad of female Rag2-/-Il2rg-/- mice, a robust model of BCa growth and metastasis." (PMID 25623198, 2015). "In our study, both IL4R and CXCR4 gene expressions were decreased with tumor progression, whereas both DOK2 and IL2RG gene expressions were increased with tumor progression." (PMID 23451142, 2013). "In contrast, the Il2rg insertion was present at 0.5 copies per cell, suggesting it is present in only half the tumor cells of this male mouse." (PMID 19461887, 2009).
tumor (continued). "Remarkably, this tumor has two insertions at Il2rg that occurred independently suggesting strong selection for Il2rg deregulation in Lmo2-initiated T-ALL." (PMID 19461887, 2009). "Surprisingly, tumor 7107 contains two Il2rg insertions, which was confirmed by conventional cloning and sequencing." (PMID 19461887, 2009). "The two Irs2 insertions must therefore have occurred first and in the same tumor cell followed by the two Il2rg insertions in different subpopulations of tumor cells." (PMID 19461887, 2009). "Our analysis spotlighted a trend wherein IL-2RG gene expression augmented concomitant with more advanced tumor stages, though the association was not statistically pronounced (p-value > 0.05)." (PMID 38720389, 2024). "To determine the in vivo relationship between the PRKCSH-IGF1R axis and NK cell-mediated antitumor effects, we used a xenograft tumor model of IL2Rg gene-deleted NOD/SCID mice (NIG mice), which was optimized to determine the antitumor effects induced by NK cells." (PMID 38200153, 2024). "This phenotype was recapitulated in LK-2 tumors that developed in Rag2–/–Il2rg–/–Cd47–/– recipient mice, where a significantly higher proportion of parental LK-2 than CALB1-deficient LK-2 2B7 tumor cells stained positive for p63, a marker for squamous epithelial differentiation encoded by TP63." (PMID 37192000, 2023). "Notably, data have shown that curcumin treatment prevents tumor-induced T cell apoptosis in tumor-bearing mice via the restoration of IL-2RG expression." (PMID 37240365, 2023). "Similarly, combination drug treatment of RCMB18 SHH MB patient-derived xenografts (PDX) in a small cohort of NOD SCID IL2Rg null (NSG) mice significantly reduced tumor growth, as single well-encapsulated nodules were observed relative to vehicle controls." (PMID 35835937, 2022). "Moreover, we evaluated the antitumor effects of SPNpro in 4T1-tumor-bearing immunodeficient NOD-Scid IL2rg−/− (NSG) mice, which lack functional lymphocytes (including T cells and NK cells) and are defective in immune functions." (PMID 34006860, 2021). "The human tumours grew faster in IL2RG−/Y pigs than in nude mice." (PMID 32871045, 2020). "One possible hint for novel developments comes from the fact that systemic treatments against NK cells administered to nude mice had a limited effect on human tumor cell spread, unlike Rag2−/−;Il2rg−/− mice which have a generalized NK deficiency." (PMID 22737248, 2012). "In addition to cell line tumors, we have also successfully generated PDX-like tissue and tissue organoids from humans and engrafted these more complex and physiologically relevant specimens into the RAG2/IL2RG knockout animals, opening the opportunity to move beyond cell line-based tumor models." (PMID 34478363, 2022). "We observed significant up-regulation of IL-15 signaling genes in tumor-infiltrating NK clusters, including IL15, IL2RB, IL2RG, STAT5B, and JAK1." (PMID 40315330, 2025). "To investigate the effects of ASNS deletion in tumor progression, we used a cell-line derived cancer xenograft Rag2/IL2RG (R2G2) mouse model and performed a tumorigenicity study to examine tumor growth in vivo." (PMID 38886847, 2024). "To generate immunodeficient Xenopus tropicalis for tumor transplantation, we employed the CRISPR/Cas9 system to simultaneously knock out prkdc and il2rg genes, which are essential for T cell, B cell, and NK cell development." (PMID 38443437, 2024). "To model FLRT3-expressing cancer in a cell line–derived xenograft (CDX) tumor model, we intradermally implanted 293T cells that ectopically expressed FLRT3 in NOD.Cg-Prkdc scid Il2rg tm1Wjl/SzJ (NSG) mice with adoptively transferred human PBMCs." (PMID 38427724, 2024). "The ability to xenograft tumor cell lines and PDX tissue in the RAG2/IL2RG knockout pigs orthotopically, provides a highly unique model for histotripsy development." (PMID 34478363, 2022).
tumor (continued). "To examine the in vivo anti-tumor activity of CTLA4-T cells toward CD80/CD86-expressing tumors, we developed subcutaneous xenograft models using NOD/SCID/IL2Rg−/− mice." (PMID 33868277, 2021). "The C4 subset was annotated as Treg cells based on the high expression signature genes of tumor-infiltrating Tregs (FOXP3, IL2RA, IL2RB, IL2RG, IL10RA, MAGEH1, LAYN, and GATA3)." (PMID 34663810, 2021). "The Lgals9-based network by Cytoscape showed extensive and complex correlation between Lgals9 and other molecules in tumor-immune microenvironment, including CD4, CD19, CD79A, CIS, IL2RG, FCGR2C, and FASLG." (PMID 33082168, 2020). "In contrast, the expressions of RAC2 (p = 0.0405), ZAP70 (p = 0.0121), IL2RG (p = 0.0175) and CD247 (p = 0.0112) were downregulated in tumour tissues." (PMID 29967488, 2018). "We investigated the ability of MFB to inhibit in vivo tumor growth, using xenograft mouse models in which MDA-MB-231 and NDY-1 cells were injected into the mammary fat pads of immunocompromised NOD/scid IL2Rg (null) (NOG) mice." (PMID 27223262, 2016). "STAT3 inhibition showed a minor, but not significant impact in tumor progression despite being implanted in Rag2/IL2rg-/- mice." (PMID 36443756, 2022). "Due to the historic use of mice in IRE and other tumor ablation modality development, we next compared the Panc01 tumors grown in this study from the RAG2/IL2RG pigs with Pan02 tumors generated in immunocompetent mice and PDX tissue derived tumor generated in immunocompromised mice." (PMID 33828203, 2021). "In tumor tissues, four protective genes (JAK2, IL2RG, EEF1E1, and UBB) showed relatively low expression in the high‐risk group; in contrast, the expression of four risk genes (EPS8, FOXO1, STAT5A, and PAPPA) was more highly in the high‐risk group than that in the low‐risk group." (PMID 34825509, 2021). "Interestingly, restoration of STAT5A and IL2RG expression has been reported to impair NPM/ALK expression in ALCL cells, thus acting as tumor suppressors in this context." (PMID 34503232, 2021). "There were also genes that are of insignificant expression in tumor cells that increase in expression in KO cells, e.g. THBS3, IL2RG, SPRR3, TGM2, HMOX1 and TMEM62 or are lower in expression in tumor cells and significantly decreased in KO cells such as MAN1A1, CES1, STCBP6, SIVA1 and TMEM40." (PMID 31797958, 2019). "To test our hypothesis that only a small population of CSCs is responsible for tumor formation, we transplanted each of the four ATC cell lines into groups of NOD/SCID Il2rg-/- mice — a highly immunocompromised strain that lacks T cells, B cells, and NK cells." (PMID 23724124, 2013). "Consistent with nongenetic cellular heterogeneity in vitro, HARA cell tumors formed in the lungs of Rag2–/–Il2rg–/–Cd47–/– recipient mice were also heterogeneous with respect to calbindin protein, with clusters of positive and negative cells in the same tumor nodule." (PMID 37192000, 2023). "Therefore, the different compartments of immune systems in these strains and the genetic background of tumor cells used in allografts and xenografts may explain the paradoxical TEI scores of IL2Rg−/− strain in allograft and xenograft tests." (PMID 26022250, 2015). "Third, although the IL4 pathway was significantly enriched in both the tumor progression and chemotherapy signatures, the IL4 gene was not differentially expressed in either of the two comparisons, and the expression levels of two receptors for IL4 (IL4R and IL2RG) were divergent." (PMID 23451142, 2013). "Similar to what was reported previously, Il2rg is not misexpressed in tumor 7107." (PMID 19461887, 2009). "Nod/Scid/Il2rg−/− (NSG) mice lack T cells, B cells, and NK cells, and NR-V04 treatment failed to inhibit tumor growth in the NSG hosts for MC38 or B16F10 tumors." (PMID 38334978, 2024). "As NK cells are not produced without il2rg, NOG mice are the most prone to tumor formation without significant immune problems in vivo." (PMID 27391353, 2016).
tumor (continued). "To substantiate the observed enhancement of IL-2RG expression within COAD, we turned to the detailed immunohistochemical (IHC) staining available within the Human Protein Atlas (HPA) repository, comparing tumor tissues against non-neoplastic colonic tissues." (PMID 38720389, 2024).